LINC02806 (long independently transcribed non-coding RNA 2806)
Synonyms: LOC124904403
Gene: Long non-coding RNA gene on chromosome 1 (148,279,161 to 148,347,802, forward strand). Ensembl gene ENSG00000238107.
Gene Ontology:
Molecular function: triplet codon-amino acid adaptor activity
Biological process: translation